IGF1 (insulin like growth factor 1)
Diseases named in the same sentence as IGF1 in open-access papers (continued):
Sharing a sentence is not in itself a finding about the gene and the disease.
hearing loss (22 papers, 2015 to 2025). "In humans, lower IGF-1 levels with age correlate with worsening hearing loss, suggesting that IGF-1 signaling modulation requires careful consideration in age-related conditions like age-related hearing loss (ARHL)." (PMID 40725452, 2025). "This study described for the first time that peg-IGF-1 carries the potential for a therapy of hearing loss." (PMID 35720065, 2022). "Less severe decreases in human IGF-1 levels have been associated with other hearing loss rare genetic syndromes, as well as with age-related hearing loss (ARHL)." (PMID 34359856, 2021). "In the present study, the enhancing effect of USMBs on the efficacy of IGF-1 application and the treatment effect of USMB-mediated IGF-1 delivery for noise-induced hearing loss (NIHL) were investigated." (PMID 34199327, 2021). "IGF-1 was protective in animal models of noise-induced hearing loss and aminoglycoside-induced hair cell loss." (PMID 34198685, 2021). "In animal studies, the intratympanic delivery of IGF-1 has preventive and therapeutic effects on noise-induced hearing loss (NIHL) and ischemic cochlear damage." (PMID 34199327, 2021). "Recombinant IGF-1 therapy has been approved to increase linear growth, and therefore height, in humans, spurring an increasing interest in the potential use of IGF-1 for the treatment of hearing loss." (PMID 29311900, 2017). "Evidence from a range of scientific disciplines implicates Insulin-like Growth Factor 1 (IGF-1) in the aetiology of hearing loss." (PMID 28646237, 2017). "Mutations in the insulin-like growth factor 1 (igf1) gene cause syndromic hearing loss in both humans and mice, supporting a role of growth factors in protecting hearing." (PMID 25954196, 2015). "Moreover, circulating levels of IGF-1 are directly correlated with the severity of hearing loss, and topical administration of IGF-1 has been associated with positive outcomes in the recovery from sudden sensorineural hearing loss." (PMID 40364096, 2025). "Here, we have reviewed human GH/IGF1 system disorders associated to hearing loss." (PMID 34680948, 2021). "Interestingly, only when IGF-1 actions are totally impaired do the affected patients show syndromic hearing loss." (PMID 29311900, 2017). "Finally, epidemiologic studies of aging cohorts have shown a relationship between bioactive IGF-1 and hearing loss." (PMID 29311900, 2017). "Thus, in younger participants (aged 50–60 y, n = 1400), IGF-1 was associated with lower odds of hearing impairment (0.86; 0.73, 1.00) after adjustment for a range of potential confounders." (PMID 28646237, 2017). "In people at the lower end of the older-aged spectrum (aged 50 to 60 years), higher levels of IGF-1 were associated with lower odds of hearing impairment and most particularly in participants free of hearing impairment at baseline, where a moderately high effect size was found." (PMID 28646237, 2017). "In the younger group, there was a statistically significant inverse linear association that remained after multiple adjustment whereby higher levels of IGF-1 were linked to lower odds of future hearing loss: OR per 5nmol/L increase in IGF-1; 95% CI: 0.86; 0.73, 1.00, p = 0.03." (PMID 28646237, 2017). "In the ear, IGF1 is currently being studied as a potential polypeptide to be used in the treatment of sensorineural hearing loss and the first results of a clinical trial involving 25 patients with sudden sensorineural hearing loss are very promising." (PMID 25954197, 2015). "Thus, the perturbation of IGF-1 signaling, as with the use of IGF-1/R inhibitors, may negatively impact the function or survival of mature SGNs, leading to the onset of otologic AEs such as hearing loss or tinnitus." (PMID 37240591, 2023). "Moreover, different IGF1 gene mutations in humans are associated with hearing loss." (PMID 34198685, 2021). "In the case of decreased sensitivity to GH, hearing impairment results from a reduction in the levels of IGF-1." (PMID 34680948, 2021).
hearing loss (continued). "More observational studies are needed to confirm our results before considering the possibility of testing low-dose supplementation in IGF-1 for long-term prevention of hearing impairment." (PMID 28646237, 2017). "In the older group, evidence of a ‘J’-shape was clearer with a p-curvature = 0.02 in the fully adjusted model and increased odds of hearing impairment were found in the top IGF-1 quintile compared to the bottom." (PMID 28646237, 2017). "This is the first population-based study to show a linear relationship between IGF-1 and hearing impairment." (PMID 28646237, 2017). "In another set of sensitivity analyses, we included only those participants with two measures of IGF-1, resulting in a sample of 3085 (n = 1153 cases of hearing impairment)." (PMID 28646237, 2017). "Insulin-like Growth Factor 1 (IGF-1) is associated with cardiovascular disease, itself a risk factor for hearing impairment, and, in animal studies, molecular evidence suggests a role for IGF-1 in hearing function." (PMID 28646237, 2017). "Our observational evidence that higher levels of IGF-1 appeared to confer some protection against hearing impairment in some older adults warrants replication in other prospective cohort studies." (PMID 28646237, 2017). "In human cohorts, decreased age-related-IGF-1 bioavailability correlates with progression of hearing impairment, as will be discussed in depth below." (PMID 29311900, 2017). "Preliminary trials have demonstrated a role of IGF-1 intratympanic injections for the treatment of refractory sensorineural hearing loss (although this has not been studied in patients whose hearing loss is related to teprotumumab)." (PMID 40680730, 2025). "While reduced IGF-1 signaling is associated with an increased lifespan, IGF-1 deficiency in animals leads to sensorineural hearing loss, increased inflammation, and loss of cell renewal mechanisms, adversely affecting the cochlea and vestibular organs, essential for hearing and balance." (PMID 39273652, 2024). "This phenomenon might be related to the RCS (restricted cubic spline) curve we derived, indicating that higher levels of IGF-1 and IGFR could result in a lower risk of hearing loss induced by BEX in obese individuals compared to normal-weight individuals." (PMID 38413886, 2024). "Following ROS production in the inner ear, changes in miRNAs alter mRNA expression; specifically, upregulation of miR-29a, miR-200c, and miR-17 occurs which in turn, downregulates insulin-like growth factor 1 (IGF-1), alters (IGF-1) mediated signaling and contributes to hearing loss." (PMID 35990888, 2022). "These complex effects of IGF-1 on vascular function may partly explain the ‘J’-shaped observed in relation to hearing impairment in the older group of our study." (PMID 28646237, 2017). "However, the link between IGF-1 and the occurrence of hearing impairment is untested in population-based studies of humans." (PMID 28646237, 2017). "However, the relationship appeared to differ according to age such that there was lower odds of hearing impairment observed at higher levels of IGF-1 among people aged below 60 years." (PMID 28646237, 2017). "Similarly, Igf1−/− mice are dwarfs with poor survival rates and bilateral profound hearing loss, while mice with reduced production of IGF-1 (Igf1−/+) do not show initial hearing loss but are more susceptible to noise-related hearing loss (NIHL) than normal mice." (PMID 37240591, 2023). "Despite a strong prima facie case for a link between circulating levels of IGF-1 and hearing impairment, to our knowledge, this relationship has not been examined in a well-characterised, free-living population of humans." (PMID 28646237, 2017). "However, no significant higher levels of hearing impairment was observed at lower levels of IGF-1 among respondents aged 60 and over." (PMID 28646237, 2017).
hearing loss (continued). "Because IGF‐1 is the key effector of growth hormones and inhibits hair cell apoptosis, we speculate that chronic suppression of IGF‐1 signalling due to reduced blood insulin levels can contribute to growth failure and hearing impairment in PFIC1 patients and Atp8b1 mutant mice." (PMID 40851490, 2025).
hypercortisolemia (22 papers, 2014 to 2026). "In MS, delayed growth and puberty are caused by inadequate tissue glucose, decreased IGF-1 levels, receptor impairment or resistance to growth hormone action, and hypercortisolism, which is the cause of cushingoid features in this condition." (PMID 40904852, 2025). "In this study, special attention was paid to cortisol, since hypercortisolemia, a common feature in SZ patients, was suggested to lead to a deficit in IGF-1." (PMID 40141202, 2025). "Hypercortisolemia would reduce IGF-1 levels either through the reduction of IGF-1 transcription or the expression of IGF-1R and GH-R." (PMID 40141202, 2025). "In the case of patients with uncontrolled GH/IGF-1 levels or severe hypercortisolism, caution and careful monitoring is needed when using SGLT-2 inhibitors due to the increased risk of diabetic ketoacidosis and genitourinary fungal infections." (PMID 39735646, 2024). "Following adrenalectomy, her cortisol levels normalized, and her IGF-1, growth hormone, and oral glucose tolerance test showed substantial improvement consistent with previous reports linking hypercortisolism and elevated IGF-1 levels." (PMID 38192880, 2023). "Insulin-like growth factor 1 (IGF-1) levels are elevated in some patients with endogenous hypercortisolism and decrease with GR antagonism." (PMID 33292727, 2020). "In particular, endocrine changes include hypothalamic amenorrhea, a nutritionally acquired growth hormone resistance with low insulin like growth factor-1 (IGF-1), relative hypercortisolemia, low leptin, insulin, amylin and oxytocin, and high peptide YY (PYY) and adiponectin." (PMID 35896857, 2022). "The expression of insulin-like growth factor 1 (IGF1) was downregulated in hypercortisolemia." (PMID 35737302, 2022). "Hormonal changes include growth hormone (GH) resistance with low insulin-like growth factor-1 (IGF-1) levels, hypothalamic hypogonadism, hypercortisolemia, and changes in appetite-regulating hormones such as leptin, ghrelin, peptide YY, and possibly adiponectin." (PMID 34207744, 2021). "Additionally, these patients present mild hypercortisolemia, low serum insulin levels, low insulin-like growth factor 1 (IGF-1) and low total triiodothyronine." (PMID 25201001, 2014). "Also, several hormonal changes occur including somatotropin resistance with low insulin-like growth factor-1 (IGF-1) levels, hypothalamic hypogonadism, relative hypercortisolemia, and changes in appetite-regulating hormones including leptin, ghrelin, and peptide YY (PYY)." (PMID 35103128, 2021). "The coexistence of paraneoplastic IGF-1 excess, ACTH-independent hypercortisolism, and an incidental pituitary lesion has not been previously reported." (PMID 41497147, 2026).
hyperthyroidism (22 papers, 2005 to 2026). Overactivity of the thyroid gland resulting in overproduction of thyroid hormone and increased metabolic rate. "In postmenopausal women with hyperthyroidism, GH level is reduced, which decreases IGF-1 protein and causes osteogenesis." (PMID 36602528, 2023). "The corresponding mutated genes set that has common effects on hyperthyroidism in children included IGF1, CACNA1S, MYH7, IL6, TTN, CACNB2, LAMA2, and DMD." (PMID 37876543, 2023). "Moreover, two-step MR analyses revealed that the risk-reducing effect of HMGCR inhibition on hyperthyroidism was partially mediated by lowering the levels of insulin-like growth factor 1 (IGF-1)." (PMID 38425755, 2024). "Besides, IGF-1 deficiency is associated with more severe FT3 hyperthyroidism." (PMID 38349236, 2024). "Additionally, it is known that hyperthyroidism is associated with increased activity of the sympathetic nervous system and with abnormalities in the growth hormone/insulin-like growth factor 1 axis, which may affect glucose homeostasis, insulin sensitivity, and ghrelin levels." (PMID 40093748, 2025). "Comorbidities were seen in >50% of diabetic cats, with hypersomatotropism suspected based on IGF-1 >746 ng/ml in 17.5% (n = 17/97) cats, and known or suspected hyperthyroidism identified in 5.8% (n = 8/139) cats." (PMID 39772828, 2025). "In cats with hyperthyroidism, serum IGF-1 concentrations increased significantly after ATD treatment, and IGF-1 levels were negatively correlated with FT4 levels after diagnosis and treatment." (PMID 38349236, 2024). "Our findings suggest that in patients with GHPA combined with GD, GD causes hyperthyroidism and after ATD was applied, GH/IGF-1 levels were significantly lower than before." (PMID 38349236, 2024). "It indicates that hyperthyroidism promotes the secretion of GH/IGF-1, which is detrimental to the biochemical control of GHPA." (PMID 38349236, 2024). "In our study, case 5 showed a significant decrease in GH/IGF-1 and an improvement in hyperthyroidism after receiving SSA treatment alone." (PMID 38349236, 2024). "Another study evaluated serum IGF-1 levels in 30 patients with GD hyperthyroidism (HY group) and patients with normal thyroid function (EU group)." (PMID 38349236, 2024). "Cases 1, 6, 7, 8, and 10 were initially treated with SSA and had a mild decrease in their GH/IGF-1 levels compared to before, as well as thyroid function showing improvement in hyperthyroidism." (PMID 38349236, 2024). "Two additional ADRs without available MedDRA preferred terms were reported in patients with GHD; one male patient had subclinical hyperthyroidism and one female had high insulin-like growth factor-1 (IGF-1) levels (667.4 ng/mL)." (PMID 27809913, 2016). "GD hyperthyroidism affects the synthesis and secretion of GH/IGF-1." (PMID 38349236, 2024). "Therefore, in patients with GHPA combined with GD, controlling GH/IGF-1 levels not only helps to avoid further worsening of hyperthyroidism due to GD but also helps to reduce the clinical activity of GO." (PMID 38349236, 2024). "Interestingly, our two-step MR analyses identified that IGF-1 served as a mediator for the protective effect of HMGCR inhibition on hyperthyroidism." (PMID 38425755, 2024). "Hyperthyroidism consistently augmented IGF-1 levels of DH mice to the same level as controls." (PMID 37654561, 2023). "Biochemistry showed elevated serum IGF1 (1,372.5 ng/mL) and secondary hyperthyroidism." (PMID 37988667, 2023). "On the other hand, high levels of GH/IGF-1 in patients with GHPA also exacerbate GD hyperthyroidism, which is ameliorated by a decrease in GH/IGF-1 levels by TSS or SSA treatment, suggesting that the GH–IGF-1 axis promotes growth, thyroid function, and thyroid hormone metabolism." (PMID 38349236, 2024).
hyperthyroidism (continued). "Two-step MR analysis revealed eighteen biomarkers linked to genetic mimicry of HMGCR inhibition, and identified insulin-like growth factor 1 (IGF-1) levels mediating 2.108% of the negative causal relationship between HMGCR inhibition and hyperthyroidism." (PMID 38425755, 2024). "Hyperthyroidism due to GD promotes the secretion of GH/IGF-1, and when thyroid hormone levels were decreased by the use of ATD, GH and IGF-1 levels were also decreased, suggesting that thyroid hormones may influence the synthesis and secretion of GH/IGF-1." (PMID 38349236, 2024). "Our study highlights HMGCR inhibition as a promising therapeutic target for hyperthyroidism, and reveals a potential mediation pathway involving the modulation of IGF-1 levels rather than lipid metabolism." (PMID 38425755, 2024). "It shows that even if hyperthyroidism is not treated with ATD, the hyperthyroid state due to GD improved with a significant decrease in GH and IGF-1 levels after TSS or SSA for GHPA." (PMID 38349236, 2024).
liver dysfunction (22 papers, 2012 to 2026). "The reduction of insulin-like growth factor 1 (IGF-1) plasma levels is associated with the degree of liver dysfunction and mortality in cirrhotic patients." (PMID 26186540, 2015). "Because of the complexity of the effect of deficient glycosylation on the GH-IGF system, the mechanism of IGF-1 deficiency in these patients could be multifactorial stemming from varying degrees of GH resistance, liver dysfunction, and inadequate nutrition/malabsorption." (PMID 26425584, 2013). "Specifically, disruption of the growth hormone insulin-like growth factor 1 axis due to liver dysfunction is an important factor that can induce growth retardation in children with chronic liver disease." (PMID 41602893, 2026). "GHD is not uncommon in adult polytransfused patients but the frequent coexistence of hepatopathy makes it impossible to use IGF-1 measurement to screen for GHD, so a dynamic test is mandatory, especially in older patients." (PMID 30356378, 2018). "However, insulin like-growth-factor 1 (IGF-1) is manufactured in the liver and its decline is one of the first markers of liver dysfunction." (PMID 31038324, 2019). "Recent studies recommended IGF-1 as a “surrogate marker for assessment of liver dysfunction”." (PMID 30064393, 2018). "The estimation of serum IGF1, IGF2 and IGFBP3, together with Child-Pugh score, is more effective in predicting liver dysfunction and its severity, compared to Child-Pugh score alone." (PMID 25225571, 2014). "Our study shows that there is no significant relation between IGF-1 and varices which can be due to presence of other concordant conditions leading to varices than liver dysfunction." (PMID 23599716, 2013). "A large-scale, prospective study should be introduced to validate the usefulness of FRAX and serum IGF-1 levels for predicting fractures in patients with PBC and age-matched controls without liver dysfunction." (PMID 36010307, 2022). "Serology showed no liver dysfunction, no statistical differences in triglyceride (TG) levels (trending higher in the HFHC cohort), & no statistical differences in insulin or IGF-1 levels (not shown)." (PMID 22279565, 2012).